ENSG00000278404
Gene: Miscellaneous RNA gene on chromosome 22 (26,657,521 to 26,657,655, forward strand). Ensembl gene ENSG00000278404.
Gene Ontology:
Biological process: cell fate specification
Cellular component: nucleus
Homologues: Orthologues: mouse Gm55685 (84% identical).